RIPK2 (receptor interacting serine/threonine kinase 2)
Diseases named in the same sentence as RIPK2 in open-access papers (continued):
Sharing a sentence is not in itself a finding about the gene and the disease.
Stroke (continued). "We hypothesize that RIPK2 plays a damaging role in the progression of stroke injury by enhancing the neuroinflammatory response to stroke and that global genetic deletion or microglia-specific conditional deletion of Ripk2 will be protective following ischemic stroke." (PMID 37777791, 2023). "Future studies should investigate the precise role of RIPK2 and NOD signaling in post-stroke cognitive impairment." (PMID 40225421, 2025). "We also showed that the absence of Ripk2 elicits neuroprotective effects after stroke regardless of the age or sex of the animals." (PMID 37777791, 2023). "Our initial evidence highlighted the dramatic decrease in infarct size after stroke in mice, where Ripk2 is globally absent." (PMID 37777791, 2023). "We next sought to assess immune cell activation after stroke in the absence of RIPK2." (PMID 37777791, 2023). "Finally, Ripk2−/− mice scored markedly lower on the neurological deficits score (NDS) test compared to WT mice, indicating greater preservation of their neurological functioning and motor coordination after stroke." (PMID 37777791, 2023). "We hypothesized that both global knockout and conditional knockout of Ripk2 in microglia would prove beneficial in reducing acute-stage neuroinflammation and preserving BBB integrity, as well as improving behavioral outcomes in these animals after stroke." (PMID 37777791, 2023).
triple-negative breast carcinoma (4 papers, 2018 to 2025). An invasive breast carcinoma which is negative for expression of estrogen receptor (ER), progesterone receptor (PR), and human epidermal growth factor receptor 2 (HER2). "RIPK2 expression is believed to be elevated in triple negative breast cancer (TNBC) and significantly correlated with worse progression in TNBC." (PMID 29874851, 2018). "Additionally, RIPK2 promotes the migration and invasion of triple-negative breast cancer cells via NF-κB and c-Jun N-terminal kinase pathways." (PMID 40406369, 2025). "In addition, high expression of RIPK2 leads to low relapse-free survival in triple-negative breast cancer patients." (PMID 35473583, 2022). "In addition, RIPK2 promotes triple-negative breast cancer cell migration and invasion through activation of the NF-kappa B and JNK pathways." (PMID 35473583, 2022). "Only one study has indicated that RIPK2 expression correlates with triple negative breast cancer." (PMID 29874851, 2018). "As reported so far, RIPK2 could activate NF-κB and JNK signaling to promote cell migration and invasion of triple-negative breast cancer." (PMID 37016317, 2023).
autoimmune disease (3 papers, 2021 to 2024). A disorder resulting from loss of function or tissue destruction of an organ or multiple organs, arising from humoral or cellular immune responses of the individual to their own tissue constituents. "Recent experimental and clinical studies have provided evidence that activation of RIPK2 is involved in the development of autoimmune diseases, especially IBDs." (PMID 33935757, 2021). "Thus, the NOD2-RIPK2 signaling pathway has attracted extensive attention due to its significant role in numerous autoimmune diseases, making pharmacologic RIPK2 inhibition a promising strategy, but little is known about its role outside the immune system." (PMID 37324457, 2023). "Consequently, RIPK2 emerges as a promising target for cancer treatment 54 and autoimmune diseases." (PMID 38164277, 2024).
cardiac hypertrophy (3 papers, 2021 to 2025). "Additionally, studies have shown that RIPK2-deficient mice exhibit better survival rates, improved cardiac function, and reduced cardiac hypertrophy following pressure overload." (PMID 40406369, 2025). "Further research indicated that RIPK2 can interact with MAVS in cardiomyocytes via CARD-CARD domain interactions, promoting NF-κB signaling, which leads to inflammation and myocardial hypertrophy." (PMID 40406369, 2025).
experimental autoimmune encephalomyelitis (3 papers, 2016 to 2023). An autoimmune demyelinating disease of the central nervous system that is produced experimentally in animals by the injection of homogenized brain or spinal cord in Freund's adjuvant. "WEHI-345, which was identified as a RIPK2 inhibitor by screening a proprietary library of 120 kinase inhibitors, delayed NF-κB activation by inhibiting polyubiquitination of RIPK2 and ameliorated experimental autoimmune encephalomyelitis." (PMID 33935757, 2021).
glioma (3 papers, 2022 to 2026). A benign or malignant brain and spinal cord tumor that arises from glial cells (astrocytes, oligodendrocytes, ependymal cells). "Among the differentially expressed genes, RIPK2 presents higher expression in TMZ-resistant glioma than in sensitive glioma." (PMID 37324457, 2023). "It is the imbalance of this negative feedback circle that leads to the malignant progression of glioma, which undoubtedly highlights the critical role of RIPK2-mediated NF-κB hyperactivation in pathogenesis." (PMID 37324457, 2023). "In the clinical setting, the expression of RIPK2 in human Glioma tissues is higher than that in normal tissues, and this high expression level is positively correlated with tumour grade." (PMID 35473583, 2022). "RIPK2 inhibits the proliferation and apoptosis of glioma cells by activating the NF-κB pathway and the mitogen-activated protein kinase (P38) pathway, and it inhibits tumour growth by regulating TRAF3 expression instead of the NF-κB pathway." (PMID 35473583, 2022). "Furthermore, RIPK2 contributes to temozolomide resistance by inducing stemness in glioma cells through the NF-κB signaling pathway." (PMID 41563982, 2026). "In GBM treatment, silencing of RIPK2 enhanced cellular sensitivity to TMZ, which offers a novel strategy for RIPK2-positive TMZ-resistant glioma." (PMID 37324457, 2023). "In addition, RIPK2 was mainly negative in Lung cancer (9/11 patients), Glioma (9/12 patients), Testicular cancer (8/10 patients) and Renal cancer (9/12 patients)." (PMID 35473583, 2022).
HCMV infection (3 papers, 2016 to 2021). "These included IDO and RIPK2, which have previously been identified as important antiviral factors during HCMV infection." (PMID 32886716, 2020). "HCMV infection of human foreskin fibroblasts induced NOD2, the downstream receptor-interacting serine/threonine-protein kinase 2 (RIPK2), resulting in phosphorylation of TANK-binding kinase 1 (TBK1) and interferon regulatory factor 3 (IRF3)." (PMID 26830977, 2016). "NOD1 induction of IFN-β depends on RIPK2, as RIPK2 knockdown does not confer the protective effects of Tri-DAP-induced IFN-β expression during HCMV infection." (PMID 33525590, 2021). "There was no significant induction of RIPK2 mRNA after HCMV infection." (PMID 26830977, 2016).
hepatocellular carcinoma (3 papers, 2013 to 2026). A malignant tumor that arises from hepatocytes. "In addition, RIPK2 also plays a role in hepatocellular carcinoma by affecting the expression of EMT-related genes." (PMID 35473583, 2022).
ischemic stroke (3 papers, 2023 to 2025). A stroke disorder caused by obstruction of blood flow to the brain, due to thrombotic (local blood clot formation) or embolic (due to a blood clot or other material traveling from another site) event. "We hypothesized that the aged Ripk2 deficient mice would have smaller infarction volumes and improved behavioral outcomes following permanent middle cerebral artery occlusion (pMCAO), a rodent model of ischemic stroke." (PMID 40225421, 2025). "Previous work in our lab has elucidated a clear role of RIPK2 signaling in the neuroinflammatory response following rodent models of ischemic stroke." (PMID 40225421, 2025). "This study is significant, because it identifies RIPK2 as a novel therapeutic target for the treatment of ischemic stroke and other neuroinflammatory conditions." (PMID 37777791, 2023). "This study assessed the acute and long-term behavioral outcomes of Ripk2−/− mice after experimental ischemic stroke and examined the extent to which microglia contribute to ischemic stroke injury by utilizing RIPK2." (PMID 37777791, 2023). "Our recent findings also demonstrated that mice with global genetic deletion of RIPK2 or conditional deletion of microglial RIPK2 showed reduced effects on infarct volume and improved neurobehavioral outcomes after ischemic stroke compared to their WT littermates." (PMID 39519307, 2024). "In this study, we utilized genetic approaches to define the role of RIPK2 in ischemic stroke." (PMID 37777791, 2023). "Gene set enrichment analysis further revealed elevated pathways and genes associated with inactivation of MAPK activity in the KO microglia, highlighting a negative role of RIPK2 in controlling ischemic stroke-induced neuroinflammation." (PMID 37777791, 2023).
lung carcinoma (3 papers, 2020 to 2022). "In addition, the immunohistochemical results of RIPK2 were consistent with the results of RNA expression and total protein, but not consistent in Lung cancer and Thyroid cancer." (PMID 35473583, 2022).
lymphoma (3 papers, 2016 to 2022). A malignant (clonal) proliferation of B- lymphocytes or T- lymphocytes which involves the lymph nodes, bone marrow and/or extranodal sites. "Immunohistochemistry showed the expression level of RIPK2 protein increased in stomach adenocarcinoma and tonsil malignant lymphoma." (PMID 35508972, 2022).
osteoarthritis (3 papers, 2022 to 2025). A noninflammatory degenerative joint disease occurring chiefly in older persons, characterized by degeneration of the articular cartilage, hypertrophy of bone at the margins and changes in the synovial membrane. "Further support for the NOD2/RIPK2 pathway was demonstrated recently in a report documenting the presence of a germline mutation in RIPK2 that resulted in a constitutively active form of RIPK2 in osteoarthritis patients." (PMID 40095546, 2025). "A change in Asn104Asp close to the active site of RIPK2 has been identified in families with osteoarthritis and is sufficient to produce a constitutively active kinase that can drive the activation of NFκB in both cell-based assays and in vivo in zebrafish." (PMID 40095546, 2025). "Receptor-interacting serine/threonine protein kinase 2 (RIPK2) regulates NLRP3 and inflammation, and the NOD/RIPK2 inflammatory signaling pathway has been found to confer susceptibility to osteoarthritis." (PMID 36619896, 2022).
stomach adenocarcinoma (3 papers, 2021 to 2024). "The study demonstrated a positive correlation between the expression of RIPK2 and the TMB and MSI in different types of tumors, including stomach adenocarcinoma (STAD)." (PMID 38164277, 2024).
thyroid cancer (3 papers, 2021 to 2025). "RIPK2 was negatively expressed in Thyroid cancer (4/4 patients), but moderately expressed in normal tissues." (PMID 35473583, 2022). "Among the six upregulated genes in ATC components, RIPK2 (receptor-interacting protein kinase 2) has been reported to be highly expressed in some cancer types, such as bladder urothelial, breast invasive, and thyroid carcinomas." (PMID 40965626, 2025). "RIPK2 not only plays an important role in inflammatory and immune diseases but is also involved in tumor invasion and metastasis and promotes immune cell infiltration, especially in thyroid carcinoma, renal clear cell carcinoma, and testicular germ cell tumor." (PMID 40965626, 2025).
ZIKV infection (3 papers, 2017 to 2023). "As a result, only a few DE PCGs involved in immune response, such as TNFSF13B and RIPK2, were upregulated by ZIKV infection." (PMID 29116029, 2017). "Several genes involved in cell death (CASP1, TNFSF10, RIPK2, and BID) were also activated upon ZIKV infection." (PMID 30781519, 2019).
bladder cancer (2 papers, 2021 to 2022). "However, RIPK2 polymorphism was also involved in the development of bladder cancer." (PMID 34692520, 2021). "Receptor-interacting serine/threonine-protein kinase 2 (RIPK2) was markedly increased in bladder cancer and a protector as demonstrated by univariate Cox analysis." (PMID 34692520, 2021).
diabetes (2 papers, 2017). "Beyond Ripk2, there is evidence for the involvement of other proteins targeted by TKI in pre-diabetes and diabetes, such as c-Abl, PDGFR, EGFR and VEGFR2." (PMID 28484277, 2017).
glioblastoma (2 papers, 2022). The most malignant astrocytic tumor (WHO grade IV). "Compared to standardized biomarkers, RIPK2 was more accurate and valuable in predicting immunotherapy outcome for patients with GBM (Zhao2019_PD1_ Glioblastoma, AUC = 0.83) or HNSC (Uppaluri2020_PD1_HNSC, AUC = 0.88)." (PMID 35508972, 2022).
HIV-1 infection (2 papers, 2015 to 2016). The type species of lentivirus and the etiologic agent of acquired immunodeficiency syndrome (AIDS). "Supporting evidence include reports showing that HIV-1 PR specifically cleaves other serine/threonine kinases, including the NDR1 and NDR1 kinases, receptor-interacting protein kinase 1 (RIPK1), and RIPK2 in CD4+ T cells during HIV-1 infection." (PMID 26982200, 2016). "RIPK1 and RIPK2 were cleaved during HIV-1 infection of T cell lines or primary activated CD4+ T cells." (PMID 26297639, 2015). "Having established that PR cleaves RIPK1 and RIPK2 during HIV-1 infection, we sought to determine whether cleavage of RIPKs deregulated host processes that may impact virus replication." (PMID 26297639, 2015). "Having established that ectopically expressed or purified HIV-1 PR can cleave RIPK1 and RIPK2 in various cell types, we next asked whether RIPK1 and RIPK2 are cleaved during HIV-1 infection." (PMID 26297639, 2015).
kidney cancer (2 papers, 2021). Primary or metastatic malignant neoplasm involving the kidney. "In addition, RIPK2 expression was low in head and neck, and kidney cancers, and leukemia in some datasets." (PMID 33633788, 2021). "In addition, inhibition of RIPK2 activity by either shRNA-mediated knockdown or inhibitor significantly reduced kidney cancer cell viability, trans-migration in vitro, and impaired tumor growth in vivo." (PMID 33790054, 2021). "In conclusion, elevated RIPK2 expression indicates a worse prognosis for KIRC patients and could serve as a potential prognostic biomarker and therapeutic target in kidney cancer." (PMID 33790054, 2021).
leukemia (2 papers, 2021 to 2024). A malignant (clonal) hematologic disorder, involving hematopoietic stem cells and characterized by the presence of primitive or atypical myeloid or lymphoid cells in the bone marrow and the blood. "Deficiency of Serpinb9b confers leukemia resistance in SPF mice, which is controlled by activation of another kinase, receptor-interacting serine/threonine-protein kinase 2 (RIPK2)." (PMID 38966643, 2024).
liver cancer (2 papers, 2019 to 2022). An epithelial or non-epithelial malignant neoplasm that arises from the liver. "RIPK2 also showed medium–high expression in Liver cancer (4/12 patients), but it was still dominated by low expression and negative expression." (PMID 35473583, 2022).
melanoma (2 papers, 2012 to 2025). A malignant, usually aggressive tumor composed of atypical, neoplastic melanocytes. "XIAP ubiquitinates RIPK2 and recruits neutrophils to inhibit growth of melanoma." (PMID 40133252, 2025). "Decreased expression of the NFκB transcription factor and the NFκB activator RIPK2 was unexpected, as UVR activates the NFκB pathway in many melanoma cells, and these cells constitutively express both NFκB and an alternative activator NIK." (PMID 22745913, 2012).
Obesity (2 papers, 2017 to 2021). Accumulation of substantial excess body fat. "This is relevant to obesity-induced metabolic disease because Ripk2 propagates inflammatory signals in response to peptidoglycan and this bacterial cell wall component can promote dysglycemia via Nod115." (PMID 28484277, 2017).
periodontitis (2 papers, 2020 to 2022). An acute or chronic inflammatory process that affects the tissues that surround and support the teeth. "Hypermethylation was found in TLR regulators genes: MAP3K7, MYD88, IL6R, RIPK2, FADD, IRAK1BP1, and PPARA in early stages of periodontitis, while advanced stages presented hypomethylation of these genes." (PMID 36233348, 2022).
rectal cancer (2 papers, 2019 to 2021). A primary or metastatic malignant neoplasm that affects the rectum. "In a recent study on four patients with CRC, RIPK2 was shown to be upregulated in rectal cancer in comparison to normal adjacent mucosa, as identified by the ChIP-Seq procedure." (PMID 34356990, 2021). "This led to the identification of genes with increased H3K27ac, i.e., RIPK2, FOXQ1, KRT23, and EPHX4, which were also highly upregulated in primary rectal cancer in an independent dataset." (PMID 31404997, 2019).
sarcoma (2 papers, 2021 to 2022). A usually aggressive malignant neoplasm of the soft tissue or bone. "In sarcoma, gefitinib blocks the invasion and metastasis of tumour cells by inhibiting RIPK2 to reprogram macrophages." (PMID 35473583, 2022).
Sepsis (2 papers, 2007 to 2022). Sepsis is defined as life-threatening organ dysfunction caused by a dysregulated host response to infection. "The H&E-staining of intestines displayed the reduced lesion area and the recovery of the intestinal barrier in Ad-Ripk2 treated Card9−/−-sepsis mice compared with Card9−/−-sepsis mice." (PMID 35618701, 2022). "We also observed that sepsis in WT mice was reduced after Ad-Ripk2 treatment." (PMID 35618701, 2022). "Analysis of cytokines and physiological indexes in serum revealed that pre-treating mice with Ad-Ripk2 could prevent sepsis in Card9−/−mice." (PMID 35618701, 2022). "The function of Ripk2 was further demonstrated in WT and Card9−/−-sepsis mice." (PMID 35618701, 2022). "Similarly, the expression of ZO-1, Occludin, Claudin-2, detected by immunohistochemistry, was increased in the intestinal tissue in Card9−/−-sepsis mice treated with Ad-Ripk2 compared with Card9−/−-sepsis mice." (PMID 35618701, 2022). "With regard to apoptosis, both pro-apoptotic (COP1, GADD45B and RIPK2) and anti-apoptotic (TNFAIP3 and BIRC3) genes were induced in the early stages of sepsis." (PMID 17324256, 2007).
tuberculosis (2 papers, 2019 to 2025). A chronic, recurrent infection caused by the bacterium Mycobacterium tuberculosis. "‘Tuberculosis’ KEGG pathway map comprised five signal transduction mediators, Irak2, Jak2, Malt1, Ripk2, and Src, regulated by induced enhancers." (PMID 30669987, 2019).
acute monocytic leukemia (1 paper, 2022). Acute monoblastic leukemia (AML-M5), is one of the most common subtypes of acute myeloid leukemia (AML) that is either comprised of more than 80% of monoblasts (AML-M5a) or 30-80% monoblasts with (pro)monocytic differentiation (AML-M5b). "PROTAC 10 can significantly degrade RIPK2 in the acute monocytic leukemia cell line THP-1 cells, which may be an effective option for treating acute monocytic leukemia." (PMID 36142231, 2022).
allergic asthma (1 paper, 2024). A asthma with a basis in a pathological type I hypersensitivity reaction. "Yahia (2021) found that deletion of NOD1 or RIPK2, but not NOD2, inhibited both BAL inflammation and airway responsiveness in response to methacholine in house dust mite (HDM)-induced allergic asthma in mice." (PMID 39507249, 2024).
Anxiety (1 paper, 2025). Intense feelings of nervousness, tension, or panic often arise in response to interpersonal stresses. "One possible explanation for this is that aged Ripk2-/- mice may have higher anxiety-like behavior than WT controls." (PMID 40225421, 2025). "The increased anxiety seen in our data could, therefore, be a result of the interplay between the lack of functional RIPK2 and advanced age in the Ripk2-/- mice used in this study." (PMID 40225421, 2025).
Arthritis (1 paper, 2023). Inflammation of a joint. "In the methylated bovine serum albumin (mBSA) induced arthritis mouse model, the contribution of RIPK2 to arthritis was highlighted by the reduction of neutrophil migration and mechanical hyper nociception in Ripk2−/− mice compared to the WT." (PMID 36959850, 2023).